INS (insulin)
Diseases named in the same sentence as INS in open-access papers (continued):
Sharing a sentence is not in itself a finding about the gene and the disease.
Hyperglycemia (continued). "The impairment of insulin sensitivity may be caused by hyperglycemia and hyperlipidemia-induced ROS or the production of ROS by-products." (PMID 36978903, 2023). "Hyperglycaemia may be caused by the loss of insulin secretion by pancreatic β-cells or insulin resistance acquired by body tissues; it is also possible that both processes coexist and contribute to disease onset." (PMID 37686290, 2023). "Furthermore, both estrogen and progestin reduce the serum levels of fasting blood sugar and insulin, which explains why hyperglycemia and hyperinsulinemia increase the risk of CRC." (PMID 37775754, 2023). "STZ causes the destruction of the pancreatic insulin-secretingβ cells, which reduces insulin and, in turn, results in a rise in blood glucose concentration, i.e., hyperglycemia; the extracts, especially PCMAX, significantly decreased the blood glucose levels in the diabetic rats." (PMID 37398913, 2023). "The occurrence of abruptio placentae and epileptic seizure may be associated with concomitant hyperglycemia, and the epileptic seizure was terminated after she underwent treatment with insulin." (PMID 37920254, 2023). "The increase in the lean mass and fat mass in the compound‐1‐treated group could be caused to enhance insulin action in tissues by reduction of hyperglycemia and hyperinsulinemia toxicity by SSTR5 inhibition." (PMID 36585794, 2023). "For example, women were less likely than men to achieve HbA1c < 7.0% even after adjustment for oral hypoglycemic agent, insulin, and statins which was associated with hyperglycemia, suggesting that other mechanisms may be involved." (PMID 37211595, 2023). "Consequently, additionally to this damage, insulin production by these cells is altered, and lost within the time that causes hyperglycemia." (PMID 37896035, 2023). "Moreover, in some individuals, genetically compromised cells fail to secrete an adequate amount of insulin, resulting in hyperglycemia, the hallmark of T2D." (PMID 37762083, 2023). "The intraoperative insulin requirement might reflect hyperglycemia and severe acid-base balance disorder, which can cause hypercoagulability, oxidative stress and endothelial dysfunction." (PMID 36744052, 2023). "NDM is classified into transient (TNDM), permanent (PNDM), or syndrome types, which have expressed significant genetic changes causing persistent hyperglycemia, reduced β-cell mass or replication, delayed pancreatic islet development, and impaired insulin secretion." (PMID 37239377, 2023). "Additional research is needed to determine whether the occurrence of glioma has a different association with abdominal obesity, hyperglycemia, and insulin-dependent carcinogenesis in comparison with other obesity-related tumors." (PMID 36928679, 2023). "Currently, there are several insulin infusion methods to control PN-associated hyperglycemia." (PMID 37674887, 2023). "β cell loss causes insufficient insulin secretion and further hyperglycemia in the body." (PMID 37298086, 2023). "Hyperglycemia together with weight loss was a sign of insulin signaling dysfunction." (PMID 37698486, 2023). "This condition of chronic hyperglycemia is caused by abnormal insulin levels." (PMID 37109046, 2023). "For example, glucocorticoid therapy given concomitantly with chemotherapy may increase T2D risk due to weight gain, reduced insulin synthesis, reduced insulin sensitivity, and hyperglycemia." (PMID 37656235, 2023). "Secondary to this step, the first phase of insulin secretion diminishes, causing hyperglycemia." (PMID 37893045, 2023). "However, hyperglycemia occurs during this process in susceptible pregnant women who are unable to compensate for insulin resistance (IR) and insufficient insulin secretion, thus resulting in GDM." (PMID 37512897, 2023). "Furthermore, the COVID-19 infection enhances insulin resistance, therefore causing hyperglycemia deterioration." (PMID 37893528, 2023).
Hyperglycemia (continued). "However, other experiments indicated that Huntingtin mutation was associated with impaired insulin synthesis and vesicular transport, suggesting that hyperglycemia was attributable to insulin deficiency." (PMID 38001993, 2023). "Considering that binge eating, i.e., consumption of a large amount of food in a short time, can reduce an individual’s insulin sensitivity and cause prolonged hyperglycemia, these data suggest that patients also experience hyperglycemia-induced limbic system inhibition." (PMID 37664841, 2023). "Furthermore, postprandial hyperglycemia predicts increased all-cause mortality and cardiovascular disease, even in individuals with normal fasting blood glucose and insulin levels." (PMID 37821856, 2023). "Furthermore, insulin-dependent glucose transporters in peripheral tissues are downregulated, causing stress hyperglycemia." (PMID 36904164, 2023). "Consuming meals rich in sugar regularly might increase the likelihood of developing pancreatic cancer by frequently causing postprandial hyperglycemia, raising insulin demands, and lowering insulin sensitivity." (PMID 37842365, 2023). "We further propose that liver SFA-related DNA methylation profile may contribute more to hyperglycemia, while insulin-related methylation profile is more linked to NAFLD or NASH." (PMID 36765383, 2023). "The degree of the stress response can be calculated through many ways like measuring the hormones (growth hormone, insulin, catecholamines, plasma concentration of cortisol, etc.), neuroendocrine sequelae, and other metabolic changes (nitrogen loss and hyperglycemia)." (PMID 37790019, 2023). "However, there has been a note from the results of this study about decreased insulin secretion as a cause of hyperglycaemia in patients with COVID-19 infection." (PMID 38192935, 2023). "Consequently, treatment with pasireotide has been associated with significant inhibition of insulin and incretins secretion, along with only a modest suppression of glucagon levels, which commonly leads to pasireotide-induced hyperglycemia." (PMID 37139336, 2023). "Hence, optimal insulin therapy for young children with T1D should provide effective glycemic control while minimizing the risk of hypoglycemia and hyperglycemia." (PMID 36800034, 2023). "Several types of exercise protocols enhance health and glycemic management in individuals with DM, although structured exercise training has been studied most frequently, with benefits resulting from enhanced insulin sensitivity, reduced postprandial hyperglycemia, and reduced cardiovascular risk." (PMID 37998439, 2023). "Patients treated with sulfonylureas (p = 0.008), insulin and metformin association (p = 0.040), insulin and sulfonylurea association (p = 0.048), and DPP4i and sulfonylurea association (p = 0.031) were exposed to a higher risk of hyperglycemia (≥180 mg/dL) at admission." (PMID 36830792, 2023). "Parabacteroides were also positively correlated with the production of SCFAs and have beneficial effects in reducing weight gain, hyperglycemia, and inflammation risk, maintaining intestinal barrier integrity, and improving insulin resistance and antioxidant enzyme activity." (PMID 37894615, 2023). "Therefore, it was reasonably concluded that Gm10451 affects the secretion of oxidative stress and inflammatory factors, which would eventually cause alterations in islet β-cell proliferation and insulin secretion under hyperglycemia." (PMID 36003336, 2022). "Furthermore, preterm infants are particularly susceptible to hyperglycemia due to immature regulatory mechanisms and decreased insulin production." (PMID 35267894, 2022). "The cell damage leads to insulin secretion disorders, causing hyperglycemia." (PMID 36523339, 2022).
Hyperglycemia (continued). "Another possibility is that the necessity of insulin prescription at dialysis initiation might reflect severely decreased insulin secretion due to β-cell dysfunction, which was caused by islet microangiopathy driven by long-term hyperglycemia." (PMID 35213636, 2022). "These events may be due to stress hyperglycemia, which is caused by insulin resistance, the interplay among hormones, and regulatory cytokines." (PMID 36079047, 2022). "Because loss of Sirt1 in the fat body alters glucose metabolism and insulin sensitivity in the organism, we expected modifiers of hyperglycemia to impact pathways linked to central carbon metabolism as well as external processes that influence secretion and signaling of hormones such as insulin." (PMID 35435227, 2022). "Therefore, the use of STZ + HFD has been reported to impair the secretions of insulin, which causes hyperglycemia and dyslipidemia, amongst other disorders." (PMID 36296534, 2022). "However, there are few studies related to MAFG in the pathogenesis of DFU progression, and only a few reports suggest that MAFG loss improves glucose metabolism and insulin sensitivity, thus protecting from hyperglycemia." (PMID 36226171, 2022). "This might be explained by a new “set point” of hyperglycemia caused by the cellular downregulation of GLUT4 transporters induced by exogenous insulin." (PMID 35842591, 2022). "For example, studies of glucose metabolism in T2D patients could be hindered due to the defects in insulin secretion and insulin signaling, which are associated with hyperglycemia, because hyperglycemic patients usually have IR independent of genetic defects." (PMID 35987697, 2022). "Hyperglycemia may affect the risk of cancer and cancer-related death through the direct mitogenic effect of insulin and the production of IGF-1 (insulin-like growth factor 1)." (PMID 36263231, 2022). "Hyperglycemia in T2DM patients is caused by impaired insulin secretion and insulin resistance (IR)." (PMID 35495933, 2022). "In addition, increased glucose and insulin levels (hyperglycemia and hyperinsulinemia) can cause molecular damage by glycation and glycoxidation, which is considered an age-related effect." (PMID 36297158, 2022). "Impaired brain insulin synthesis and malfunctioning of neuronal glucose transporters have been shown to negatively affect synapse activity and cause brain hypoinsulinemia and hyperglycemia." (PMID 36232867, 2022). "The precise mechanisms underlying this association remain unclear but glucose neurotoxicity, hyperglycemia, insulin resistance and vascular injury are likely to be involved." (PMID 36163029, 2022). "Impairment of insulin secretion and defects in insulin action frequently coexist, which may be the primary cause of hyperglycemia." (PMID 35480484, 2022). "In addition, GLUT2 deficiency in the pancreatic β-cell impairs insulin secretion, leading to hyperglycemia." (PMID 35757134, 2022). "However, hyperglycemia precisely results from β-cell loss or inability to produce and secrete insulin." (PMID 35656076, 2022). "To further examine a protective role for DSG2 in β-cell function, we challenged the mice with streptozotocin (STZ), an alkylating agent that targets the insulin-producing β-cells in the pancreas, thus mimicking β-cell loss and hyperglycemia characteristic of type 1 diabetes." (PMID 36309486, 2022). "In both cases, insulin-deficient hyperglycemia could be completely normalized when glucagon signaling was abolished, without any insulin substitution." (PMID 35456307, 2022). "An insulin sliding scale was introduced to control the associated hyperglycaemia." (PMID 35822088, 2022).
Hyperglycemia (continued). "The goal of intensive insulin therapy is to mimic physiological insulin release by pancreatic beta cells in a basal-bolus fashion to achieve tight glycemic control and thereby reduce the risk of micro- and macrovascular complications of hyperglycemia." (PMID 35733769, 2022). "Finally, hyperglycemia is presumed to be the significant determinant causing β-cells to lose differentiation, resulting in dysfunctional insulin secretion." (PMID 36992767, 2022). "STZ leads to significant hyperglycemia associated with a significant decrease in serum insulin." (PMID 36316746, 2022). "Diabetic ketoacidosis can also appear when the interruption of insulin secretion is intentional, for example, when the child participates in physical competitions, with the risk of subsequent hyperglycemia and hypoglycemia that can alter neurocognitive function." (PMID 36422210, 2022). "An insulin pump therapy was significantly associated with a higher hyperglycemia rate compared to treatment by five injections (p=0.0001), while a regimen “morning-evening” was significantly associated with a higher PHH rate compared to treatment by five injections (p=0.03)." (PMID 35832426, 2022). "During acute illness, the release of hormones that counter-regulate insulin and an excess cytokine action may cause the so-called stress hyperglycemia, even in persons with formerly normal glucose metabolism." (PMID 36992740, 2022). "Due to insulin deficiency or resistance caused by hyperglycemia, the insulin levels were tested." (PMID 36111301, 2022). "Due to insulin resistant, hepatic glycogen synthesis is reduced while gluconeogenesis is increased, which eventually leads to the increased rate of hepatic glucose output and causes hyperglycemia." (PMID 35721172, 2022). "In vivo and in vitro studies show that hyperglycaemia leads to an overexpression of Bax, (Bcl-2-associated X), which is a death-promoting protein associated with increased apoptotic morphological changes and is reversed by insulin." (PMID 36078559, 2022). "It is worth mentioning that differential factors between HNF4A-MODY and HNF1A-MODY, besides altered cholesterol and triglycerides profiles, include the MODY1 patient’s progressive hyperglycemia associated with impaired insulin secretion that worsens with time and normal renal threshold for glucose." (PMID 36361703, 2022). "Previous studies indicated that insulin therapy may be associated with increased cardiovascular events and mortality.Treatment with regular insulin may result in postmeal hyperglycemia and an increased risk of late postprandial hypoglycemia." (PMID 35047039, 2022). "Therefore, IL-6 reduces hepatic insulin sensitivity and glucose uptake by adipocytes and causes elevated plasma insulin levels, hyperglycemia, and hyperlipidemia." (PMID 35276970, 2022). "Insulin obstruction and powerlessness to react suitably to hyperglycemia cause T2DM." (PMID 35268815, 2022). "Salivary CRP and insulin were significantly associated with intermediate hyperglycemia at the 75th percentile cutoffs suggesting that a predictive value of the biomarkers such as levels found in serum could be indicative of diseases." (PMID 35757631, 2022). "The underlying pathogenesis of COVID-19–related hyperglycemia can be described by the damage to pancreatic β-cells and decreased insulin sensitivity and altered insulin secretion due to the activation of the renin-angiotensin system (RAS) and the host’s inflammatory response to COVID-19." (PMID 35336774, 2022). "Hyperglycemia also leads to excessive mitochondrial metabolism in β-cells, leading to alterations in the mitochondrial shape, volume and behavior as well as K-ATP channels, thus causing obstruction in glucose-mediated insulin secretion." (PMID 35164215, 2022).
Hyperglycemia (continued). "Basic research of hepatic inflammation showed that AIS could activate the pathway of hepatic inflammation via catecholamine and cause hepatic insulin resistance, followed by hyperglycemia, generating lesions in hepatic function eventually." (PMID 36061892, 2022). "We next investigated whether GAPDH inhibition alone was sufficient to cause changes in glucose metabolites and insulin secretion resembling those produced by chronic hyperglycaemia." (PMID 36376280, 2022). "Considered a significant risk to health and survival, type 1 diabetes (T1D) is a heterogeneous autoimmune disease characterized by hyperglycemia caused by an absolute deficiency of insulin, which is mainly due to the immune-mediated destruction of pancreatic beta cells." (PMID 36704045, 2022). "It is typical that development of overweight is associated with slightly accelerated height rate, but here the children experienced weight loss due to deteriorating endogenous insulin secretion and gradual development of hyperglycemia and polyuria before the diagnosis." (PMID 35244713, 2022). "Therefore, high-dose PFOA consistently causes fasting hyperglycemia, but more studies are needed to resolve the variability in glucose tolerance and insulin secretion results." (PMID 35156417, 2022). "Reactive hypoglycaemia refers to low blood sugar that is relatively uncommon, where a high-sugar meal induces hypoglycaemia, due to a rapid increase in blood sugar levels (hyperglycaemia), causing an insulin overproduction and triggering a rapid drop in blood sugar levels." (PMID 35627115, 2022). "We could not determine if the negative association with adult height was due to the abnormal insulin response or due to hyperglycemia." (PMID 35358060, 2022). "Thus, elevated fetal insulin secretion in response to fetal hyperglycemia results in fetal hypoglycemia which causes gluconeogenesis and fat oxidation aberrations." (PMID 36558427, 2022). "In addition, we elucidated the molecular mechanism underlying GnIH-mediated hyperglycemia and dyslipidemia: GnIH disturbed the synthesis of insulin and glucagon in the pancreas as well as fatty acid biosynthesis and fatty acid oxidation in eWAT." (PMID 35897643, 2022). "In this context, recombinant TRAIL treatment has been shown to ameliorate streptozotocin-induced diabetes in mice by reducing hyperglycemia, preventing catabolic manifestations such as weight loss, and partially preserving pancreatic islet morphology and residual insulin secretion." (PMID 35328646, 2022). "In long term, chronic hyperglycemia, metabolic abnormalities (gluco- and lipo-toxicity) and oxidative stress eventually lead to progressive β-cell loss and failure with subsequent decreased insulin secretion, which further impairs the glycemic control." (PMID 36012137, 2022). "Hyperglycemia is associated with worse cognitive performance, resulting from insulin dysregulation, expression of insulin-degrading enzymes, and severe hypoglycemic events that might damage the structure of the brain." (PMID 35252292, 2022). "This milder glucose dysregulation in the ELD group may be due to their more prominent use of anti-glycemic agents, or to delayed insulin secretion upon food intake that causes transient and mild post-prandial hyperglycemia." (PMID 36558885, 2022). "Thus, hypokalemia is associated with the development of hyperglycemia through the impairment of potassium-dependent insulin release in response to glucose overload." (PMID 35334607, 2022). "However, chronic long-term hyperglycaemia can cause β-cells to pathologically decompensate and fail to meet the insulin demand, it further in turn leads to β-cell dysfunction and the development of T2DM." (PMID 36232419, 2022). "This suggests that the reduced HbA1c in Val carriers could be mediated through amelioration of postprandial hyperglycemia linked to mechanisms that alter glucose absorption, instead of beta-cell function or insulin sensitivity." (PMID 35662939, 2022).